KRTAP4-2 (keratin associated protein 4-2)
Description:
In the hair cortex, hair keratin intermediate filaments are embedded in an interfilamentous matrix, consisting of hair keratin-associated proteins (KRTAP), which are essential for the formation of a rigid and resistant hair shaft through their extensive disulfide bond cross-linking with abundant cysteine residues of hair keratins. The matrix proteins include the high-sulfur and high-glycine-tyrosine keratins.
Synonyms: KAP4.2; KRTAP4.2
Tractability: No criterion of Open Targets' tractability assessment is met for any kind of drug.
Gene: Protein-coding gene on chromosome 17 (41,177,446 to 41,178,221, reverse strand). Ensembl gene ENSG00000244537.
Pathways (Reactome):
Developmental Biology: Keratinization
Gene Ontology:
Molecular function: identical protein binding; protein binding
Biological process: hair cycle
Cellular component: cytosol; keratin filament
Genetic constraint (gnomAD): Loss-of-function variants: 0 observed, 0.38 expected, observed/expected ratio (o/e) 0, 90% interval 0 to 1.85. That is too few expected variants to judge how well the gene tolerates losing a copy. Missense variants: 178 observed, 178.72 expected, observed/expected ratio (o/e) 1, 90% interval 0.88 to 1.13. Synonymous variants: 56 observed, 61.88 expected, observed/expected ratio (o/e) 0.9, 90% interval 0.73 to 1.13.
Homologues: Orthologues: chimpanzee KRTAP4-2 (97% identical), macaque KRTAP4-2 (96% identical), mouse Krtap4-16 (65% identical), rat Krtap4-3 (65% identical), mouse Krtap5-24 (45% identical), mouse Krtap5-2 (42% identical), mouse Krtap5-26 (42% identical), rat Krtap5-8 (40% identical), rat AABR07006049.1 (39% identical), mouse Krtap5-20 (35% identical). Paralogues in human: KRTAP4-12 (82% identical), KRTAP4-9 (79% identical), KRTAP4-11 (79% identical), KRTAP4-5 (79% identical), KRTAP4-6 (78% identical), KRTAP4-7 (78% identical), KRTAP4-4 (77% identical), KRTAP4-8 (73% identical), KRTAP4-3 (72% identical), KRTAP4-1 (62% identical), KRTAP10-12 (54% identical), KRTAP10-7 (52% identical), and 35 more.
Diseases named in the same sentence as KRTAP4-2 in open-access papers:
KRTAP4-2 is named in the same sentence as 2 diseases in open-access papers, as found by Europe PMC text mining. Sharing a sentence is not in itself a finding about the gene and the disease. The quoted sentences say what the papers report.
cystic teratomas of the ovary (1 paper, 2022). "Among the prevalent mutated genes, 7 with the same variant in exons with changes in protein coding are important for the development of mature cystic teratomas of the ovary: PTGFRN, DUSP5, MPP2, PHLDA1, PRR21, GOLGA6L2, and KRTAP4-2." (PMID 36289533, 2022).
KRTAP4-2 also shares sentences with these, for which no sentence is quoted: cancer (1 paper).